RPSA2 (ribosomal protein SA 2)
Description:
Required for the assembly and/or stability of the 40S ribosomal subunit. Required for the processing of the 20S rRNA-precursor to mature 18S rRNA in a late step of the maturation of 40S ribosomal subunits. Also functions as a cell surface receptor for laminin. Plays a role in cell adhesion to the basement membrane and in the consequent activation of signaling transduction pathways. May play a role in cell fate determination and tissue morphogenesis. Also acts as a receptor for several other ligands, including the pathogenic prion protein, viruses, and bacteria. Acts as a PPP1R16B-dependent substrate of PPP1CA.
Synonyms: 37LRP; LRP/LR; 67LR; LamR; LBP/p40; RPSAP58; RPSA_30_1642
Gene: Protein-coding gene on chromosome 19 (23,762,944 to 23,871,162, forward strand). Ensembl gene ENSG00000288920.
Subcellular location: Cell membrane; Cytoplasm; Nucleus
Gene Ontology:
Molecular function: laminin binding; laminin receptor activity; structural constituent of ribosome
Biological process: cytoplasmic translation; ribosomal small subunit assembly; cell adhesion; translation
Cellular component: cytosolic small ribosomal subunit; cytoplasm; nucleus; plasma membrane; ribosome; small ribosomal subunit
Genetic constraint (gnomAD): Loss-of-function variants: 6 observed, 6.91 expected, observed/expected ratio (o/e) 0.87, 90% interval 0.47 to 1.64. That is too few expected variants to judge how well the gene tolerates losing a copy. Missense variants: 118 observed, 133.11 expected, observed/expected ratio (o/e) 0.89, 90% interval 0.76 to 1.03. Synonymous variants: 47 observed, 47.47 expected, observed/expected ratio (o/e) 0.99, 90% interval 0.78 to 1.26.
Homologues: Orthologues: macaque RPSA (99% identical), mouse Rpsa (98% identical), guinea pig RPSA (98% identical), chimpanzee RPSA (95% identical), tropical clawed frog rpsa (93% identical), zebrafish rpsa (92% identical), dog RPSA (90% identical), Drosophila melanogaster sta (56% identical), Caenorhabditis elegans rps-0 (53% identical). Paralogues in human: RPSA (99% identical).
Diseases named in the same sentence as RPSA2 in open-access papers:
RPSA2 is named in the same sentence as 4 diseases in open-access papers, as found by Europe PMC text mining. Sharing a sentence is not in itself a finding about the gene and the disease.
RPSA2 shares sentences with these, for which no sentence is quoted: epilepsy (1 paper); glioblastoma (1); Infertility (1); leukemia (1).